RN7SL270P (RNA, 7SL, cytoplasmic 270, pseudogene)
Gene: Miscellaneous RNA gene on chromosome 17 (47,041,825 to 47,042,105, forward strand). Ensembl gene ENSG00000277198.
Homologues: Orthologues: chimpanzee Metazoa_SRP (99% identical), macaque Metazoa_SRP (93% identical), macaque Metazoa_SRP (91% identical), rabbit Metazoa_SRP (68% identical). Paralogues in human: Metazoa_SRP (99% identical), RN7SL199P (99% identical), RN7SL656P (99% identical), RN7SL404P (95% identical), RN7SL1 (84% identical), RN7SL3 (84% identical), RN7SL2 (84% identical), RN7SL804P (81% identical), RN7SL45P (81% identical), RN7SL333P (80% identical), RN7SL712P (80% identical), RN7SL88P (80% identical), and 707 more.